BRCA1 (BRCA1 DNA repair associated)
Diseases named in the same sentence as BRCA1 in open-access papers (continued):
Sharing a sentence is not in itself a finding about the gene and the disease.
tumor (continued). "BRCA1 is a tumor suppressor with DNA repair function through homologous recombination in response to DNA double-stranded breaks." (PMID 31023256, 2019). "Data on the stroma-tumor crosstalk indicated that caveolin-1 (CAV1) and breast cancer type 1 susceptibility protein (BRCA1) involved in oxidative stress pathway in CAFs." (PMID 31014370, 2019). "All these observations, together with our results, suggest that, in the absence of the BRCA1-UbcH5a complex, the maintenance of the binding with BARD1 is dispensable for the BRCA1 tumor suppressor activity." (PMID 30696104, 2019). "When homologous recombination repair defects present in tumor cells (such as BRCA1 and BRCA2 mutations) that make DSB damage unrepairable, PARP inhibitors and homologous recombination repair defects react in the lethal synthesis of tumor cells." (PMID 31775908, 2019). "On the other hand, YY1-dependent positive regulation of BRCA1 and HP1alpha results in tumor suppression and reduced invasiveness." (PMID 31824839, 2019). "In WGS, c.5339T>C, L1780P in BRCA1 was continuously detected in buffy coat, primary tumor, F1, F2, and F3 tumors." (PMID 31821346, 2019). "We examined heterogeneity of these associations with respect to the mutation carried (BRCA1 vs BRCA2), menopausal status, tumour histology, and tumour grade." (PMID 31213659, 2019). "As the causative mutations are distributed throughout the genes, we here recommend that that the technique is suitable to detect variants in BRCA1 and BRCA2 and other tumor suppressor genes." (PMID 31131559, 2019). "This is indicative of a bigger awareness in terms of preventive diagnosis for this tumor type, especially following the publicity received by the BRCA1 and BRCA2 genes due to the “Jolie effect”." (PMID 31159747, 2019). "To test whether the elevated numbers of point mutations and structural variants in BRCA1/2-mutated samples are due to biological differences or are accounted for by the availability of more DNA, we identified copy number variants in the genomes of these 81 tumor samples using Control-FREEC." (PMID 31182087, 2019). "In this regard, mounting evidence suggests that BRCA1-mediated transcriptional regulation plays previously under-appreciated roles in tissue-specific tumor suppression." (PMID 30995943, 2019). "The concordance rate between tumor BRCA test results and germline BRCA1/2 status was 87%, with five cases harboring pathogenic/likely pathogenic somatic-only mutations." (PMID 31653094, 2019). "The tumor suppressor BRCA1 plays a key role in DSB repair via homologous recombination (HR) pathway, and BRCA1 KD mice accumulate DSBs in neuronal genomes, although the role of HR in postmitotic neurons is unclear." (PMID 31801573, 2019). "Our integrate approach revealed a profound effect of MYC overexpression on tumor evolution and identified MCL1 as a critical and druggable dependency in BRCA1-deficient TNBC with high expression of MYC." (PMID 30674894, 2019). "To determine the correlation between the expression of DNA repair genes and the inhibition of tumor growth by miR-205-5p injection, we stained tumoral tissues of the sacrificed mice for BRCA1 and RAD17 expression." (PMID 31514456, 2019). "In contrast to the tumour samples that showed detectable p‐BRCA1 in etoposide‐treated animals, RD‐N noticeably inhibited the expression of p‐BRCA1, which was correlated with positively stained CTSB and elevated γH2AX in the samples." (PMID 30565390, 2019). "BRCA1 and 2 are two major regulators of DNA double-strand break (DSB) repair through homologous recombination (HR) and play a crucial role as tumor suppressor genes, likely by preventing mutations and genome instability." (PMID 31547326, 2019). "BRCA1/2 status was evaluated on formalin-fixed, paraffin-embedded tumor specimens using next-generation sequencing technology." (PMID 31653094, 2019). "Recently, Illumina Inc. offered the TruSight Tumor 170 panel targeting 170 genes including BRCA1 and BRCA2." (PMID 31029168, 2019).
tumor (continued). "Mutations in the BRCA1 and BRCA2 genes are perhaps the most well-known causes of hereditary BC due to their disruption of the genes' tumor-suppressing functions." (PMID 31528229, 2019). "In light of our findings, it is prudent to consider the BRCA1 status and tumor hypoxia as potentially important clinical parameters affecting the therapeutic efficacy of HDAC inhibitors." (PMID 31273285, 2019). "Depletion of CTSS by shRNA delayed tumor growth in a xenograft mouse model, only in the presence of functional BRCA1." (PMID 30006610, 2019). "To elucidate the direct relationship between CTSS and BRCA1 in tumorigenesis, we examined tumor development after injection of sh-CTSS-, sh-BRCA1- or double sh-CTSS/sh-BRCA1-MDA-MB-231 cells using an SCID xenograft mouse model." (PMID 30006610, 2019). "Further studies demonstrated that BRCA1 loss is the driver mutation in hereditary and sporadic breast cancer, casting doubt on BECN1′s role as a tumor suppressor." (PMID 31027346, 2019). "Suppressing BRCA1-IRIS expression using shRNA or activity using memetic inhibitory peptides blocks TNBC tumor formation and their metastatic ability and significantly prolongs patients’ survival." (PMID 31014367, 2019). "First tested in vitro, thedrug selectively targeted tumor cells with BRCA1,BRCA2, or PTEN gene alterations with 20-to more than 200-fold greater potency than existing PARP1/2 inhibitors (such asolaparib, rucaparib, and veliparib) (Shenet al., 2013)." (PMID 31067289, 2019). "Many tumor suppressor genes, such as BRCA1/2 and CDKN2A/B, are frequently silenced by DNA methylation and inactive chromatin marks." (PMID 31497535, 2019). "Despite there being a large number of potential biomarkers, there is only a limited number of prognostic and diagnostic tumor biomarkers that are approved of (e.g., mammaglobulin, CK19—BC diagnosis; BRCA1 and 2 gene mutations—OC diagnosis)." (PMID 31443309, 2019). "The majority of these off-label indications were BRCA1 or BRCA2 mutations (90/111; 81%), which were documented across 20 different tumor types." (PMID 30658646, 2019). "For BRCA2 versus BRCA1 tumors, univariate analysis showed that tumor grade, ER, PR, HER2, CK5, CK14, and CLDN3 were independent parameters of BRCA2 status." (PMID 31307407, 2019). "While these factors are biochemically distinct, they are both synthetic lethal with loss of the BRCA1 and BRCA2 tumor suppressor genes, and hence are emerging therapeutic targets." (PMID 31381562, 2019). "Potentially actionable mutations detected from initial IDHWT tumours included EGFR, PTEN, BRCA1, BRCA2, ATM, and ATR." (PMID 32082376, 2019). "Although earlier studies suggested that BAP1 function is through modulation of the BRCA1, later studies showed that it is an independent tumor suppressor gene." (PMID 30716094, 2019). "We further applied both strategies to seven blood samples and five matched FFPE tumor tissues of patients with known germline exon-spanning deletions and gene-wide duplications in BRCA1/2 to evaluate CNV detection based solely on panel NGS data." (PMID 31029168, 2019). "We showed that these mRNA targets for lncRNAs in the ceRNA network included a variety of tumor-associated genes, such as the apoptosis-related genes FAS, BCL2, and BCL2L11 and the DNA repair gene BRCA1." (PMID 30984308, 2019). "sh-CTSS group showed the most effective tumor delay response, while sh-BRCA1 group showed similar tumor development with that of sh-Control group." (PMID 30006610, 2019). "BRCA1 is a multifunctional protein that activates ER-a transcriptional activation and tumor suppression." (PMID 33860286, 2019). "In HGSOC, tumors harboring BRCA1/2 mutations demonstrated a higher neoantigen burden, as well as CD3+ and CD8+ tumor-infiltrating lymphocytes." (PMID 31109041, 2019). "The joint role of BRCA1 and BRCA2 in HR is thought to explain their common disease phenotype, but BRCA1 also has tumor-suppressive effects through other functions." (PMID 31683985, 2019).
tumor (continued). "A more detailed examination ofmorphologic features of the tumors has shown that when compared to sporadic BCs,BRCA1 tumors exhibited higher mitotic counts, more lymphocytic infiltration andgreater proportion of the tumor with a continuous pushing margin." (PMID 31067289, 2019). "The tumor size of most of the tumors in all of the three groups (45% of BRCA1, 53% of BRCA2, and 63% of WT tumors) was < 2 cm." (PMID 31307407, 2019). "BRCA1/2 carriers now can have targeted therapies that apply parp-inhibitor to facilitate DNA repair process in tumor cell." (PMID 31477031, 2019). "Clinically, the low expression of the BRCA1/RAD17 signature in HNSCC tumor samples was found to be significantly anti-correlated with miR-205-5p expression and associated with high recurrence." (PMID 31514456, 2019). "The majority (87%) of BRCA1/2 samples fell into clusters 3 & 4, although BRCA1/2 mutant tumours that fell outside these clusters often had evidence of HRD, albeit with increased probability of unrelated signatures (e.g. L-Dup in cluster 6)." (PMID 30794536, 2019). "We found that a variety of tumor progression-related genes were involved, such as apoptosis-related genes (FAS, BCL2, and BCL2L11) and a gene associated with DNA repair (BRCA1)." (PMID 30984308, 2019). "IHC analysis of tumor xenograft samples further indicated that the protein levels of γH2AX and cleaved caspase-3 were notably increased, but BRCA1 was decreased upon circAKT3 inhibition." (PMID 30927924, 2019). "BRCA1 is a tumor suppressor that is involved in a handful of important cellular processes, among which its role in HR and transcriptional regulation in DDR draws the most attention." (PMID 31508509, 2019). "Due to compromised homologous recombination (HR) repair, BRCA1‐ and BRCA2‐mutated tumours accumulate DNA damage and genomic rearrangements conducive of tumour progression." (PMID 31273933, 2019). "As expected, disruption of Palb2 and Brca1/2 sensitized tumor cells to DNA damaging agents in vitro and in vivo." (PMID 31877165, 2019). "The calculated allele/peak ratio of the three STRs consistently confirmed LOH in the tumor, indicating the presence of a large deletion encompassing BRCA1 (17q12–17q21.31)." (PMID 30634417, 2019). "Mutational analysis of BRCA1 led to the discovery of the modular BRCT domain and its characterization as an essential component of the tumor suppressive function of BRCA1." (PMID 31771139, 2019). "Specially, a panel of eight serum tumor markers (AFP, β‐HCG, CA125, CA15‐3, CA19‐9, CA242, CEA, and HE4) showed a good performance in prediction of BRCA1 mutation carriers (AUC = 0.974, Sensitivity = 0.714, Specificity = 1.000)." (PMID 30972954, 2019). "Rad50, Rad51, Rad54b, Mre11a, Palb2, Brca1 and Bard1 all showed significantly higher expression in resistant tumours compared to responding tumours (p = 0.05, p < 0.001, p < 0.001, p < 0.001, p = 0.002, p < 0.001 and p = 0.012 respectively)." (PMID 31080552, 2019). "This mutation is located within the phosphoprotein-binding C-terminal BRCT domain which is critical for the tumor suppression function of BRCA1 gene." (PMID 31477031, 2019). "That is, either of the two mechanisms will lead to release more sponged miR-9 into tumor tissues, which subsequently reduces the endogenous suppressive effect of BRCA1, DNAJB6 and KLF4." (PMID 31623606, 2019). "This prognostic impact was unrelated to BRCA1/2 mutation status as we observed comparable results in the subgroup of patients with BRCA1/2 wt tumours." (PMID 31181781, 2019). "Tumor tissue from FFPE samples was available from all five patients with known heterozygous exon-spanning germline deletions in BRCA1 (P16-P20)." (PMID 31029168, 2019).
tumor (continued). "We demonstrate that an adjusted targeted capture-based enrichment protocol is superior to commonly applied multiplex PCR-based protocols for reliable BRCA1/2 variant detection, including CNV-detection, using FFPE tumor samples." (PMID 31029168, 2019). "BRIP1 interactions related to BRCA1 function suggested that BRIP1 have attracted the attention as a candidate tumor suppressor gene." (PMID 30975222, 2019). "As a key player in the homologous recombination-based DNA repair pathway, BRCA1 acts as a tumor suppressor via maintaining genome integrity." (PMID 31023256, 2019). "The immunomodulatory effects of niraparib in the human tumor microenvironment were further evaluated in the niraparib-sensitive BRCA1 mutant MDA-MB-436 TNBC tumors established in humanized NOG-EXL mice." (PMID 30755715, 2019). "On the other hand, as a tumor suppressor, HOXA9 inhibits the tumor phenotype by regulating the expression of BRCA1 in breast cancer." (PMID 31013831, 2019). "We demonstrate that chlorambucil has high selective toxicity against human cells and xenograft tumours with compromised BRCA1/2 function." (PMID 31273933, 2019). "BRCA1 is a tumor suppressor gene, which contributes to DNA repair and transcriptional regulation in response to DNA damage, and protects the genome from damage." (PMID 31794429, 2019). "Palb2-, Brca1- or Brca2- deleted tumor cells exhibit dramatically elevated sensitivity to DNA damaging drugs compared to KPC cells in vitro." (PMID 31877165, 2019). "All five germline BRCA1-deletions were also detected in FFPE-derived tumor DNA by the targeted capture-based NGS combined with the CNV calling pipeline." (PMID 31029168, 2019). "The authors also observed an increase in DNA hypermethylation of tumor suppressor genes, such as Brca1." (PMID 31547326, 2019). "Moreover, the 100% concordance was also observed between mutation detection in CS and FFPE in two cases of somatic mutations alluding that cytology samples could replace tumor tissue in determining BRCA1/2 mutation status in patients with HGSC where FFPE is hardly available." (PMID 30940100, 2019). "Taken together, our results suggest that TGF-β1 knockdown inhibits tumor growth and increases chemosensitivity by promotion of BRCA1/Smad3 signaling." (PMID 30594239, 2018). "In fact, we could hypothesize that, given that BRCA1/2-mutated high grade serous ovarian cancers (HGSOCs) exhibit a higher mutational load and a unique mutational signature, with an elevated number of larger indels up to 50 bp, these tumors may also harbor more tumor-specific neoantigens." (PMID 29731958, 2018). "The universality of the extensively characterized DSB repair activity of BRCA1 stands in stark contrast to its tissue-specific tumor suppressor function." (PMID 29426838, 2018). "We observed epigenetic silencing of important tumor suppressors, including BRCA1, MGMT, and RASSF1A exclusively in NSGCTs." (PMID 29898407, 2018). "Considering that the knockdown of BRCA1 caused reduction of the FADD level, we suggest that the loss of BRCA1 (or its inactivation) in a tumor can cause reduced levels of FADD that in turn desensitizes cells to a FasL-mediated anti-proliferative effect." (PMID 29757984, 2018). "Synthetic lethality between BRCA1 and PARP1 can be exploited through treatment of HR-deficient tumor cells with PARP inhibitors, while sparing normal cells which are HR competent." (PMID 30120226, 2018). "Co-immunoprecipitation (coIP) demonstrated that in mouse Brca1 null tumor cells, PIN1 interacted with LYN." (PMID 30590041, 2018).
tumor (continued). "DNA was extracted from formalin-fixed paraffin-embedded (FFPE) archival tumour material and sequenced using the Ion Ampliseq BRCA1 and BRCA2 panel." (PMID 29298688, 2018). "The BRCA1 protein is a tumor suppressor that has a crucial role in maintenance of genomic integrity." (PMID 30327455, 2018). "Among others, these include BRCA1/2 and Fanconi anemia tumor suppressors, which protect stalled DNA replication forks from degradation by MRE11 and DNA2 nucleases and so suppress genome instability." (PMID 29475976, 2018). "Genetic testing detected double pathogenic nonsense germline mutations in BRCA1 c.188T>A (p.L63X) and in BRCA2 c.6922A>T (p.K2308X), which were identical to the variants detected in tumor." (PMID 31608315, 2018). "Together, these results indicate that estrogen promotes EMT and proliferation of Brca1-deficinet tumor cells leading to tumor progression, which is dependent on the activation of the Akt pathway." (PMID 29996906, 2018). "To evaluate a range of tumor BRCA1/2 testing approaches, we conducted a study with ten clinical laboratories to determine the ability of a spectrum of tumor BRCA1/2 testing workflows to accurately identify tBRCA variants in clinical practice." (PMID 29215764, 2018). "Here, we summarize recent findings concerning the roles of BRCA1 in transcriptional regulation and discuss their potential contributions to the tissue- and lineage-specific tumor suppressor functions of BRCA1." (PMID 30558184, 2018). "This supports the function of P38 as a tumour suppressor, and the mechanism is substantiated by the link between p-P38 and DNA repair markers including nuclear BRCA1 and RAD51 in the current study." (PMID 30352570, 2018). "The exact role of BAP1 has not been entirely elucidated, earlier reports suggesting that the tumor suppressor function is linked to deubiquitinating BRCA1; however, later studies have indicated that BAP1 is a BRCA1-independent tumor suppressor." (PMID 29946532, 2018). "We show for the first time that knockdown of TGF-β1 suppresses tumor growth and promotes the chemosensitivity of OC cells to cis-platinum, in that we observed a BRCA1 expression increase and the activation of Smad3." (PMID 30594239, 2018). "Inhibition of autophagy by CQ during chemotherapy diminishes the expression of DNA repair proteins, resulting in tumor growth inhibition in carboplatin-resistant BRCA1 wild-type TNBC orthotopic xenografts." (PMID 29774126, 2018). "This adjustment was required because the expected proportion of observed unmethylated copies is dependent on the ratio of unmethylated somatic copies to tumor copies at the BRCA1 locus." (PMID 30266954, 2018). "We also showed that RNAP IIO ubiquitination was completely dependent on the presence of recombinant BRCA1/BARD1 and that the tumor-associated BRCA1 mutation C61G, which disrupts the RING domain, abolished RNAP IIO modification." (PMID 29180510, 2018). "Two final cases (#7, 8) had heterozygous BRCA1 methylation in both the archival sample and matched pre-treatment tumor biopsy." (PMID 30266954, 2018). "Significantly higher RASSF1 methylation levels were observed in cases positive for BRCA1/2 mutation (p=0.008), HER2 expression (p=0.01), and with high tumor grade (G3) (p=0.008)." (PMID 29731982, 2018). "Myriad tumour testing, which comprised BRCA mutation testing, BRCA1 methylation testing and determining HRD score, was performed in 219 tumour samples." (PMID 30353044, 2018). "As a tumor-suppressor gene, BRCA1 plays a pivotal role in cell-cycle regulation and DNA damage repair, and its defects result in defective cell-cycle checkpoints and genome instability." (PMID 29872500, 2018). "A higher median Myriad MyChoice® HRD score was observed in BRCAm and BRCAwt tumours with BRCA1 methylation." (PMID 30353044, 2018).